TLR3 (toll like receptor 3)
Diseases named in the same sentence as TLR3 in open-access papers (continued):
Sharing a sentence is not in itself a finding about the gene and the disease.
infection (continued). "In murine PCM, the absence of TLR3 generated greater resistance to infection, with decreased pulmonary fungal burden and an increased protective response mediated by IFN-γ and IL-17-producing CD8T cells." (PMID 33194839, 2020). "Infection of SJL mice with TMEV activates various cellular proteins via TLR2 and TLR3." (PMID 33069239, 2020). "For clusters and heterozygosity models, infection status was not influenced by any parameter except a negative association with elevation in TLR1LA, TLR3, TLR4 as top model." (PMID 33209285, 2020). "Inborn errors of TLR3- and IRF7-dependent type I IFN immunity can underlie life-threatening COVID-19 pneumonia in patients with no prior severe infection." (PMID 32972995, 2020). "During infection with SARS-Cov-2, which has a single strand RNA genome, both TLR3/TLR7 senses the presence of viral RNA, the mimic induced CSS in lung may not affect by blocking of TLR3 signaling." (PMID 33584719, 2020). "The infection of FHC and HT29 cells with EV71 resulted in a robust increase in the levels of TLR3 mRNA (top) and TLR3 protein (bottom), indicating that EV71-induced TLR3 may play a potential role in antiviral activity." (PMID 33203755, 2020). "Furthermore, cellular infiltrates, possibly immune cells, within the pancreata of these patients had high expression of TLR3 and TLR4, indicating the induction of a proinflammatory innate immune response to an infection." (PMID 32635205, 2020). "MyD88, TLR2, TLR3, and TLR4 peak at 48, 24, 12, and 36 h after infection." (PMID 31947624, 2020). "We first followed the infection of two different cell lines (DHF and TLR3-/-)." (PMID 33505391, 2020). "Thus, unexpectedly TLR3-/- cells appeared to be less sensitive than DHF cells at a 0,1 MOI infection by HSV-1 and to have comparable sensitivity at 0,5 MOI." (PMID 33505391, 2020). "Plasmacytoid dendritic cells from IRF7-deficient patients produced no type I IFN on infection with SARS-CoV-2, and TLR3−/−, TLR3+/−, IRF7−/−, and IFNAR1−/− fibroblasts were susceptible to SARS-CoV-2 infection in vitro." (PMID 32972995, 2020). "To further investigate the LRV-inhibition of the NLRP3 inflammasome in human cells, we measured IL-1β and Casp1 p20 in response to L.g.− and L.g.+ infection in cells treated with KCl (which impairs potassium efflux and activation of NLRP3) or Poly:IC (TLR3 agonist)." (PMID 31754185, 2019). "Confirming our previous experiments, L.g.+ infection induced increased ear thickness compared with L.g.− in C57BL/6, but not in Nlrp3−/−, Asc−/−, Casp1−/− or Tlr3−/− mice." (PMID 31754185, 2019). "To determine the PRRs and cytokine levels following the infection of the H5N6 viruses at the early stage, we further tested the expression of TLR3, TLR7, MDA5 mRNA and a set of representative cytokines in the brains and lungs of chickens at 24 h postinfection using qRT-PCR." (PMID 31717638, 2019). "Strikingly, while L.g.− -derived EVs did not affect IL-1β production upon infection by both clones, L.g.+-derived EVs rescued L.g.− capacity to impair inflammasome activation in WT macrophages in a TLR3-dependent manner." (PMID 31754185, 2019). "To determine the PRRs and cytokine levels following the infection of the H5N6 viruses at the early stage, we further measured the expression of the TLR3, TLR7, RIG-I mRNA, and a set of representative cytokines in the brains and lungs of mice at 3 and 5 DPI using qRT-PCR." (PMID 31717638, 2019). "We found that total numbers of subepithelial TLR3+, MDA5+, and RIG-I+ cells were each induced by rhinovirus infection in asthmatic patients in vivo, and numbers of TLR3+ and MDA5+ cells during infection were increased in asthmatic patients compared with control subjects." (PMID 29698627, 2019). "Comparably to IFNβ expression, infection with RV16 induced gene expression of TLR3, RIG-I, and MDA5 in M1-primed macrophages but there was no induction of these pattern recognition receptors in M2-primed macrophages." (PMID 31527772, 2019).
infection (continued). "The induction of cytokines (IL6 and TNFα), chemokines (CCL2 and CXCL10), and IFN-I genes in primary C57BL/6 astrocytes following a TMEV-BeAn infection can be mediated by TLR3 but not TLR7 or other MyD88-mediated pathways." (PMID 30669615, 2019). "The expression of Tlr3 and its co-receptor Mex3B is unaltered by infection in epithelium, stroma, and non-PMN immune cells." (PMID 31554802, 2019). "MHC II expression on NK cells of TLR3 KO mice, by contrast, did not change after infection in statistics (5.94 ± 2.25% versus 5.97 ± 0.94%, P > 0.05)." (PMID 30246036, 2018). "In contrast to the liver tissue, significant upregulation of TLR3, TLR4, and TLR10, but downregulation of TLR7, characterized hepatocytes derived from livers of animals with resolved AH accompanied by secondary occult infection." (PMID 30581424, 2018). "Further studies are also warranted to explore the dynamic interplay between EV-A71 2A-mediated counteract and TLR3-mediated type IFN induction, which might have a critical impact on the outcomes of EV-A71 infection." (PMID 30563052, 2018). "However, by day 21 post-infection, the frequency of CD4+ T-cells in the genital tract of wild-type and TLR3-/- mice was significantly different." (PMID 29624589, 2018). "In the present study, only TLR3 was slightly upregulated (FC 1.05) (data not shown) in head kidney samples after the infection with the wt isolate infection, at least at the time point tested." (PMID 30065724, 2018). "It is unclear why the endogenous TLR3 mRNA level in SK-N-SH cells was not upregulated upon EV-A71 infection." (PMID 30563052, 2018). "Likewise, silencing of TLR3 in human monocyte-derived dendritic cells (MoDCs) led to lower IFN-β and TLR3 mRNA expression in response to EV-A71 infection." (PMID 30563052, 2018). "The expression of NKG2A/C/E on TLR3− NK cells significantly increased after infection (70.23 ± 0.6203% versus 77.18 ± 1.348%, P < 0.05), while the percentage of NKG2D on TLR3− NK cells was significantly decreased after infection (61.08 ± 3.683 versus 13.64 ± 1.682, P < 0.05)." (PMID 30246036, 2018). "Hela cells, known to have functional TLR3 and RIG-I innate PRRs, were infected with the −ve sense ssRNA virus, sendai virus (SeV), and the upregulation of IFN mRNA examined as various time points post infection." (PMID 29293661, 2018). "In addition to the reconstitution experiments, our data from the siRNA knockdown analyses further corroborated the function of endogenous TLR3 in triggering IFN-β expression in primary macrophages and dendritic cells upon EV-A71 infection." (PMID 30563052, 2018). "Splenocytes were isolated 5 weeks after infection, and the noninfected wild-type and TLR3 knockout mice were sacrificed as the control groups." (PMID 30246036, 2018). "A subset of in ovo dsRNA treated and control groups were observed for the expressions of TLR3 and type I interferon (IFN)s, mRNA expression of interleukin (IL)-1β and macrophage recruitment coinciding with the time of H4N6 LPAIV infection (24 h post-treatment)." (PMID 29530062, 2018). "In addition, the TLR3 and IL6 mRNA levels were increased in HDAC1-depleted cells infection with IAV." (PMID 29312300, 2017). "Specifically, TLR4 recognizes the lipopolysaccharide (LPS) of gram-negative bacteria, while TLR3 recognizes viral double-stranded RNA (dsRNA), which is a common intermediate of viral replication and a potent indicator of infection." (PMID 28198368, 2017). "To address the question whether in these cells PA28 is involved in controlling redox and protein homeostasis during infection, we examined polyI:C-treated bone marrow derived macrophages (BMM) 24 and 48 hours after TLR3-stimulation." (PMID 28278207, 2017). "There was a moderate up-regulation for TLR-3 and TLR-7 in CK/SD/w3 and CK/SD/w4 infection." (PMID 27446066, 2016).
infection (continued). "TBEV induced up-regulation of RIG-I and MDA5 as early as by 24 h p.i., whereas no detectable TLR3 and p-IKKε were seen during the process of infection in T98G cells (data not shown)." (PMID 27576490, 2016). "Through multiple techniques, we demonstrate that IL-10, PDL1 and iregDC generation are not specifically dependent on direct infection or recognition of intracellular viral replication by the LCMV sensors TLR3 or MAVS." (PMID 26808628, 2016). "We elicited LCMV primed T cells in congenic wild type mice, purified CD4+ T cells on day 8 post-infection at the peak of T cell expansion, and adoptively transferred the cells into naïve Myd88-/-, IL-1R-/-, TLR2, 3, 4, 7, 9-/-, TLR3, 7, 9-/- and wild type mice." (PMID 27542117, 2016). "Influenza A virus (IAV) infection of DCs did not induce IL-12p70 but markedly upregulated TLR3 expression that during coinfection with S. pneumoniae significantly enhanced IL-12p70 secretion." (PMID 26956584, 2016). "Mast cells used TLR3, RIG-I and MDA5 to sense viral RNA following infection." (PMID 28127293, 2016). "Since TRIF mediates the signals from both TLR3 and TLR4 into the cell and pneumolysin has been suggested to activate TLR4, we first set out to investigate whether TLR4 is activated by T4R in our infection model." (PMID 26956584, 2016). "However, the expression of TLR3 and TLR7 was downregulated in response to SS-10 infection at 72 hpi (0.61 and 0.41-fold, respectively)." (PMID 26635752, 2015). "In our study, the expression of Rig-1, Mda5, and Tlr3 was upregulated in the brain and spleen during the period of infection tested, although the expression of Tlr3 was not upregulated in the spleen at 3 dpi." (PMID 26005441, 2015). "Rig-1, Mda5, and Tlr3 are involved in the host immune response to DTMUV, and the expression of proinflammatory cytokines (Il-1β, –2, –6, Cxcl8) and antiviral proteins (Mx, Oas, etc.)are also upregulated early in infection." (PMID 26005441, 2015). "Moreover, many genes exhibited different levels of expression of the various isoforms under infection with one PRRSV strain vs. the other (PARP14, SOCS1, IFIT1, MX1, IFOTM1, RNASEL, PIKSCD and TLR3)." (PMID 24643046, 2014). "Also, this result was in contrast with a previous study in which TLR3−/− mice showed reduced cytokine (e.g., TNF-α and IL-6) responses, BBB permeability, neuroinvasion, and mortality following infection with mammalian cell-passaged WNV." (PMID 25188232, 2014). "Since miRNAs are involved in viral pathogenesis and the innate response to infection, we sought to identify changes in miRNA expression upon infection in the presence or absence of TLR3." (PMID 25127040, 2014). "TLR3 has been shown to influence WNV pathogenesis both positively and negatively in vivo, by aiding in mounting a protective immune response and by enhancing infection and neuropathogenesis." (PMID 25127040, 2014). "Human XCR1+ DCs uniquely respond to stimulation with HCV by producing large amounts of IFN-III in a TLR3-dependent manner, irrespective of their own infection." (PMID 25400632, 2014). "Such a model would be consistent with our profiling data, as we observed dramatic RNA changes already at early times (2–4 hours) after infection, whereas TLR3-dependent phosphorylation of IRF3 was not induced until much later (36 hpi)." (PMID 25127040, 2014). "To characterize the mechanism underlying the IL-1β response in NHBE cells, we measured receptor transcript levels; we also assessed the efficiency of specific knockdowns of TLR3, RIG-I, and NLRP3 in primary NHBE cells at 13 h post-infection (time of peak transcriptional response to IAV)." (PMID 23592984, 2013). "The lack of TLR3 expressing MNCs from vaccinated pigs coincides with their protection from VirHRV infection." (PMID 24098572, 2013). "The levels of TLR3-4 and TLR7-9 were increased 3 h after hMPV infection." (PMID 24039959, 2013).
infection (continued). "The combination of TLR3 and 9 agonists did not result in a synergistic effect and the infection by Sendai virus resulted in much higher levels of IFNs (data not shown)." (PMID 22952664, 2012). "As following TLR3 stimulation, we couldn’t find statistically significant differences in IFN-α production between males and females following TLR9 stimulation or infection with HSV-1." (PMID 22768144, 2012). "Already, several murine models of infection have shown that early TLR3-induced IFN-β secretion does not play its expected anti-viral role but is rather involved in the eruption of a pathological immune response." (PMID 22919688, 2012). "In the current study, PR/8 infection up-regulated mRNA levels of RIG-I and MDA-5 mainly at 4 hpi, but the mRNAs of TLR3 and 7 mainly at 24 hpi, which suggests that RLHs might be the early sensors and TLRs might be the late sensors for PR/8 in human AM." (PMID 22396727, 2012). "Similar to IFN-α response following TLR7 stimulation, the production of IL10 in response to TLR3, 7, 8 ligands or following infection with PR8 was not dependent on “in vivo” stimulation by sex hormones and/or Cortisol." (PMID 22768144, 2012). "The real-time RT-PCR also revealed that the changes on gene expression of IL-10, GNA13 and TLR3 are not significantly changed at these early time points even at 100 MOI infection." (PMID 22028943, 2011). "For example, a recent study demonstrated that the absence of TLR3 did not alter viral pathogenesis after infection with single-stranded or double-stranded RNA viruses, such as lymphocytic choriomeningitis virus, vesicular stomatitis virus, and reovirus." (PMID 22189096, 2011). "Finally, after S. suis invasion of the central nervous system, transcriptional activation of TLR2, TLR3 and CD14 has been observed in a mouse model of infection." (PMID 21635729, 2011). "Although infection of cells with CVB3 is sensitive to IFNβ, we observed less enhancement of IFNβ promoter activity as assessed by luciferase activation in CVB3-infected HEK293 cells overexpressing MAVS, MDA5, RIG-I, and TLR3/TRIF than in uninfected controls." (PMID 21436888, 2011). "The idea that TLR3 could respond to dsRNA, a common viral PAMP, led to intense speculation about its role in the host response to numerous infections." (PMID 21994762, 2011). "In order to determine if TLR-3 and MyD88 signaling might have an impact on type I IFN production, supernatant from infected BMDCs was collected at various times post infection, and a VSV-sensitivity assay was performed." (PMID 20661430, 2010). "In the absence of infection, reactivity with anti-CD63 antibody and weak signal from EEIA-expressing early endosomal structures showed neuronal TLR3 to be confined to the endosomal compartment, associated mainly to the late endosomes and multivesicular bodies." (PMID 19247444, 2009). "Following RABV infection, TLR3 is not only present in endosomes, as observed in the absence of infection, but also in detergent-resistant perinuclear inclusion bodies." (PMID 19247444, 2009). "Our observation is similar to previous studies showing the non-involvement of TLR3 during induction of innate response following infection with Sendai virus (a mouse parainfluenza virus)." (PMID 19922606, 2009). "Specifically, mice lacking TLR3 had decreased viral replication, morbidity, and mortality following infection with vaccinia virus." (PMID 18802464, 2008). "Since both MDA5 and TLR3 have been shown to be involved in type I IFN and cytokine signaling in response to infection with other RNA viruses, we were interested to see if they may play a role in MNV-1 infection." (PMID 18636103, 2008). "Since the TLR3 levels and IFN responses increased in the infections with Us3 or Us3 and ICP4 deletion viruses, it could be conceivable, that US3 and/or ICP4 might act as inhibitors of TLR3-mediated signaling." (PMID 19025601, 2008).
infection (continued). "Monitoring the expression of RNA-sensing receptors like TLR3, TLR7 and RIG-I during the different clinical stages of infection could bring a new source of data about the prognosis of disease." (PMID 18021446, 2007). "Our findings also demonstrate that severity of infection and survival correlate with different PRRs between these two blood components; in leukocytes, TLR5 positively correlated and TLR7 negatively correlated with ordinal score, while in platelets, TLR3 was positively correlated." (PMID 40825056, 2025). "Additionally, infection with H9N2 AIV, whether live or inactivated, induces strong innate antiviral and inflammatory responses involving TLR3, TLR7, MDA5, TNF-α, and CCL5 stimulation." (PMID 41331407, 2025). "The same author noted that infection with Newcastle disease virus (NDV) stimulates the recognition of viral components by host cells, particularly the recognition of RNA by Toll-like receptor 3 (TLR3), which subsequently activates the TIRAP-dependent signaling pathway." (PMID 40655137, 2025). "CD69 is one of the early activation in the cells, the higher level of it in TLR3 KO mice may mainly reflect that the absence of TLR3 signaling trigger mechanisms early activation status during infection." (PMID 38172683, 2024). "Infection with DTMUV strongly increased the expression of a set of type I IFN genes and key ISGs (Mx1, OAS1, IFITM3, and OASL) through activation of the molecular adaptors MDA5 and TLR-3 involved in the RLR and TLR pathways, respectively, leading to decreased viral replication." (PMID 38793692, 2024). "Mayotte 2008 infection also induced upregulation of specific genes such as CAPS1, MYD88, and TLR3." (PMID 37306630, 2023). "However, no such upregulation of TLR3 transcripts was found in zebrafish when infected by the Gram-positive Mycobacterium marinum, while the expression of TLR3 increased after the infection of Gram-negative Edwardsiella tarda in zebrafish." (PMID 36670828, 2023). "However, the expression patterns of TLR3 in different fishes are not the same after infection with viruses." (PMID 36670828, 2023). "IEIs of TLR3-, IRF7-, UNC93B1-, TICAM1-, TBK1-, and interferon alpha and beta receptor subunit 1 (IFNAR1)-dependent type I interferon immunity have been described to underlie life-threatening COVID-19 pneumonia in patients with no prior severe infection." (PMID 37559153, 2023). "Indeed, a synergistic increase of TLR3, RIG-I, and IFN-β transcripts was demonstrated after concomitant in vitro infection of lung slices with swIAV H1N1 and PRRSV-2, although the level of replication of either virus was not reduced compared to single-infected conditions." (PMID 37287962, 2023). "Importantly, viral RNA levels measured at 72 h post-infection were similar in the TLR3-activated cells versus the non-activated cells for the passaged virus (right curves)." (PMID 36271143, 2022). "The resistance to TLR3-mediated inhibition was already observed for the viral populations harvested at passage 4 and at the different MOIs applied, thus likely independent of the infection of one cell by infectious units containing several virions." (PMID 36271143, 2022). "Taken together, these data indicate that the expression of TLR3, RIG-I, MDA5, and the phosphorylated forms of NF-κB and IRF3 are normally induced in inflammatory epithelial cells derived from patients with CRSwNP when infected with RV 16 infection or treated with poly (I: C)." (PMID 36341332, 2022). "In the mouse infection model, the RSV F protein was reported to be an effector to trigger the production of IFN-β via interaction with TLR4; while in monocyte-derived dendritic cells (mDCs), the soluble G protein was demonstrated to inhibit TLR3/4-mediated IFN-β production." (PMID 35308390, 2022).